INS (insulin)
Diseases named in the same sentence as INS in open-access papers (continued):
Sharing a sentence is not in itself a finding about the gene and the disease.
diabetes (continued). "Treatment of drug-naïve type 2 diabetes with continuous insulin infusion targeting near-normal range of glycemia for 2 weeks resulted in diabetes remission in about half of the patients at 1 year." (PMID 32597475, 2020). "Exogenous insulin, used as a therapeutic agent for diabetes, forms insoluble deposits containing amyloid fibrillar structures near the administration site." (PMID 32499589, 2020). "Diabetes of first category is mostly distinguished by inadequate production or reduced response to key regulatory hormone insulin during body’s metabolism." (PMID 33118125, 2020). "Nevertheless, a few cases were diagnosed as type 1 diabetes mellitus because of their impaired insulin secretion and necessity of insulin therapy." (PMID 33324347, 2020). "Moreover, rodents with genetic mutilation of fusion markers (Mfn2 and OPA1) suppressed OXPHOS and insulin-stimulated ATP synthesis and caused a dysregulation of glucose homeostasis and insulin signaling, which leads to an impairment of the of obese-related insulin resistance and diabetes." (PMID 32927647, 2020). "Diabetes Mellitus (DM) is a complex metabolic disorder with characteristic hyperglycemia that arises either due to defective insulin secretion by pancreatic islets or due to insulin resistance of peripheral tissues or deregulated hepatic glucose production." (PMID 32742851, 2020). "Gänsslen, in 1925, first reported the blood glucose-lowering effect of inhaled insulin (a 51-amino-acid peptide, 5.7 kDa) in five subjects with diabetes." (PMID 33114726, 2020). "Currently, a combination of autoantibodies to insulin, GAD65, IA-2 and ZnT8 are often used to assess diabetes risk." (PMID 32314012, 2020). "Most diabetic patients are type 2 diabetes mellitus (T2DM), with a major cause of deficient insulin signaling or insulin resistance." (PMID 32188147, 2020). "One limitation of this study is its small sample size, which prevents meaningful assessment of accuracy as a function of stage of pregnancy, type of diabetes, use of insulin, or sensor location." (PMID 32324061, 2020). "Pharmacological inhibition of glycosphingolipid synthesis has been shown to have a beneficial effect on insulin sensitivity and glycemic and weight control in animal models of obesity and diabetes." (PMID 32914148, 2020). "Type 1 Diabetes Mellitus (T1DM) affects the capacity of the pancreas to produce insulin and affects the Blood Glucose (BG) regulation mechanisms in the body." (PMID 32668724, 2020). "Of those utilizing only other diabetes medications than insulin or metformin in 2016 and surviving until Jan 1, 2018 (n = 726), 6.8% started using metformin and 5.9% insulin in addition to other diabetes medications than insulin or metformin in 2017." (PMID 33246453, 2020). "The purpose of this extensive study was to identify predictors of cardiometabolic risk profile based on different imaging analyses, glucose tolerance, insulin sensitivity, family history of diabetes and untargeted serum metabolomics." (PMID 32561768, 2020). "Many studies have shown that ghrelin inhibits glucose-stimulated insulin release from both human as well as rodent models of diabetes mellitus." (PMID 32325912, 2020). "There are different types of diabetes mellitus (DM) depending on the insulin production by the pancreas or the insulin effects on cells." (PMID 32290181, 2020). "Studies have also indicated that inflammatory cytokines such as IL-1β, TNF-α, and IL-6 which are increased in obesity and diabetes conditions modulate insulin signaling." (PMID 33293987, 2020). "Studies have shown that ascorbic acid supplementation can reduce blood glucose, increase insulin synthesis and secretion, improve insulin resistance, and reduce the occurrence and development of complications of type 2 diabetes mellitus (T2DM)." (PMID 33157992, 2020).
diabetes (continued). "A recent report summarized Japanese cases including the patient's age, insulin level, BMI, HbA1c, autoimmune disease, immunomodulation therapy, treatment for diabetes, and presence of hypoglycemia." (PMID 32337291, 2020). "STZ is a naturally occurring alkylating antineoplastic agent that is particularly toxic to insulin-producing beta cells in the pancreas and thus induces experimental diabetes mellitus (DM) and diabetic complications, including DN." (PMID 32190104, 2020). "Experimental studies have shown that tea has protective effects against diabetes by enhancing insulin action, ameliorating insulin resistance, scavenging free radicals, and decreasing inflammation." (PMID 32081975, 2020). "Reduced cell mass or function can both lead to insufficient insulin levels, which can result in hyperglycemia and diabetes." (PMID 33250773, 2020). "To better understand the impairment of peripheral insulin sensitivity in individuals with diabetes, we investigated three ectopic fat depots (and adjusted for V/S fat volume ratio)." (PMID 32630360, 2020). "The serum insulin levels decreased after 30 days of the experiment in the diabetes-induced (group II; 6.43 ± 0.26 μU/ml) rats compared to the control (group I; 16.94 ± 0.42 μU/ml) rats." (PMID 31953455, 2020). "The key role of glucagon in diabetes pathogenesis has largely been described by Professor Roger Unger in his scientific production, and α-cell dysfunction and insulin unresponsiveness have been suggested and researched." (PMID 33020399, 2020). "Diabetes is a group of metabolic diseases characterized by hyperglycemia resulting from insufficient insulin secretion, impaired response to insulin, or both." (PMID 33261658, 2020). "Considering the most commonly prescribed drugs, in diabetes mellitus (diabetes only or with hypertension), it was Metformin 67.8% (n = 3951), followed by Glimepiride 33.4% (n = 1946) and insulin which was prescribed to 19.8% (n = 1153) patients." (PMID 32028918, 2020). "Streptozotocin (STZ) causes apoptosis of β-cells by DNA alkylation and production of oxidative markers resulting in impaired insulin-glucose homeostasis and ultimately diabetes." (PMID 32626781, 2020). "Treatment of diabetes mellitus is generally conducted by insulin injection and the consumption of antidiabetic oral drugs." (PMID 33110487, 2020). "Overall, our results indicate that SMA micelles are capable of the oral delivery of bioactive compounds like insulin and can be effective tools in the management of diabetes." (PMID 33120872, 2020). "Type 1 diabetes mellitus (T1DM), which was previously known as insulin-dependent, or childhood diabetes, is characterized by a deficiency in insulin production and, thus, requires constant administration of exogenous insulin." (PMID 33233346, 2020). "A Swedish study assessed the four islet autoantibodies: GAD (GADA), insulinoma antigen-2 (IA2A), zinc transporter 8 (ZnT8A), and insulin autoantibodies (IAA) at the time of diagnosis of diabetes in a pediatric population." (PMID 32528556, 2020). "Insulin mutations impair differentiation of β-cells in a patient-derived iPSC model of neonatal diabetes and triggers ER-stress concomitantly with insulin expression." (PMID 33198288, 2020). "Conversely, activation of RTKs with their ligands, including growth factors and insulin, is used to treat diabetes and neurodegeneration." (PMID 33209247, 2020). "The determination of serum insulin concentration is one of the most important tests for diabetes typing and evaluating islet function and insulin resistance in diabetes." (PMID 32506749, 2020). "The association was more prominent in those with a younger age at diabetes onset and receiving treatment with both oral glucose-lowering medication and insulin." (PMID 32671413, 2020). "PCPs in Trinidad treating diabetes at the public primary care clinics face several barriers in administering proper insulin therapy." (PMID 32957991, 2020).
diabetes (continued). "Diabetes pathogenesis encompasses oxidative stress, inflammation, insulin malfunctioning and partial or total insulin secretion impairment, which leads to a constant hyperglycemia." (PMID 33143027, 2020). "Only about 23% had ever prescribed insulin for outpatient with type 2 diabetes mellitus (T2DM) in their practice while 58% routinely prescribed multivitamin supplements alongside anti-diabetic medications." (PMID 32611395, 2020). "In a pre-diabetes/diabetes phenotypes, the increased production of insulin is accompanied by augmented IAPP levels." (PMID 32265649, 2020). "Diabetes management involves insulin injections, dietary control and adjustment of doses in relation to exercise and insulin sensitivity during the day." (PMID 31900132, 2020). "This includes diabetic ketoacidosis (DKA), a dangerous and acute complication of diabetes that occurs when the body has reduced insulin." (PMID 32967730, 2020). "Pre-diabetes represents a transitional state of hyperglycemia as resistance to insulin becomes above normal but below the diabetes threshold." (PMID 32679640, 2020). "FGF21 administered to animals with diabetes and obesitydecreases their BW and blood glucose/insulin levels, improvesblood lipid profile, and increases insulin sensitivity (Bon-Durant, Potthoff, 2018)." (PMID 33659800, 2020). "It would be interesting in the future to subject spheroids to conditions which resemble obese adipose tissue to be used for diabetes or obesity studies, such as by long term insulin treatment or high glucose and fatty acid levels." (PMID 33273595, 2020). "Our new data indicate that ghrelin expression is permissive for the usual CRR to insulin-induced hypoglycemia in mice in which diabetes was induced by STZ." (PMID 33042003, 2020). "Administration of alloxan leads to inhibition of insulin secretion, resulting in persistent hyperglycemia or diabetes." (PMID 32848717, 2020). "Expression of PPARα and GLUT4 are highly downregulated in individuals affected with diabetes, and both play a major role in the regulation of glucose, lipid metabolism and transports glucose from the circulation into insulin-sensitive cells, respectively." (PMID 33317106, 2020). "The transgenic piglets exhibited the pathophysiological characteristics of diabetes, including high glucose level and reduced insulin secretion from the small and irregularly formed Langerhans Islets." (PMID 32575461, 2020). "Clinical observations that are typically used to predict RT2D include early age of onset, longer duration of diabetes and the presence of microvascular/macrovascular complications, as well as insulin use and the overall complexity of the therapeutic regimen." (PMID 32899513, 2020). "For almost a century, hormone replacement therapy using insulin has been the preferred choice for treatment of diabetes." (PMID 33158929, 2020). "At 22 weeks of age, they then became hyperglycemia with decreased insulin level due to the decline in insulin secretion from pancreatic β-cells, resulting in increased water intake, a typical symptom of diabetes." (PMID 32973311, 2020). "Diabetes mellitus (DM) is a group of chronic metabolic disorders characterized by hyperglycemia due to insufficient secretion of insulin or insulin resistance." (PMID 32641151, 2020). "The mean age of the study participants was 65.3 ± 10.2 years, mean BMI was 30.4 ± 5.2 kg/m2, mean diabetes duration was 10.3 ± 6.8 years, mean insulin treatment duration was 5.4 ± 5.0 years and mean baseline HbA1c was 8.2% ± 1.5%." (PMID 32071879, 2020). "For many years, thereby, science has been challenged to improve the quality of life and increase adherence to the treatment for diabetics, especially through the development of insulin delivery systems." (PMID 33121199, 2020). "This pinpoints that both insulin and oral medicines can further create an impact on health conditions of diabetes patients." (PMID 32215269, 2020).
diabetes (continued). "Treatment for diabetes included insulin pumps, insulin injections, and lifestyle modifications (diet and exercise)." (PMID 33209554, 2020). "Whiles the pathophysiology of cognitive dysfunction in diabetes mellitus is putative; hyperglycaemia, vascular disease, hypoglycaemia, and insulin resistance are thought to play important roles." (PMID 32245444, 2020). "A small group of children with newly diagnosed diabetes and treated with insulin also received PTX (1200–2400 mg/day)." (PMID 33153226, 2020). "In terms of main pathogenesis, type 1 diabetes mellitus (T1DM) is characterized by insufficient insulin secretion, whereas type 2 diabetes mellitus (T2DM) is characterized by low physiological utilization of insulin." (PMID 32166013, 2020). "The major class of medications included: diabetes medications, injectable insulin, statins, blood pressure lowering, pain, mood (SSRIs), bisphosphonates, steroids, thyroid hormone, and proton pump inhibitors." (PMID 32983729, 2020). "Type 2 Diabetes mellitus (T2DM) is a metabolic disorder due to impaired insulin action and secretion." (PMID 32987623, 2020). "Nocturnal hypoglycemia is a serious complication of insulin-treated diabetes, and it is often asymptomatic." (PMID 33204733, 2020). "The effect of insulin on peripheral macrophages has been studied extensively, particularly in the context of obesity and diabetes." (PMID 33100956, 2020). "What is more, our results indicated that PUFA attenuated gestational diabetes in STZ-induced diabetes rats, as reflected by the decline of fasting blood glucose and the increase of plasma insulin level and hepatic glycogen content." (PMID 33110438, 2020). "The inhibition of α-GLU can thus have an impact on diabetes treatment due to the reduction of intestinal absorption and decrease of post-lunch insulin values, maintaining the glycemic variations under control." (PMID 32580356, 2020). "Impairment of insulin signaling, such as by induction of a diabetes model via streptozotocin in rats, can significantly worsen the outcome of a SCI." (PMID 33100956, 2020). "“Weight Loss” still worked outstandingly in the algorithm as common correlations were related to the gastrointestinal tract, blood-forming tissues, diabetes, kidneys, insulin, liver, and the cardiovascular system." (PMID 32459809, 2020). "Later, the discovery of insulin would transform diabetes care, providing the first effective treatment for diabetes management and consequently increasing the prevalence and phenotypic diversity of DR (and other complications)." (PMID 32295293, 2020). "The baseline demographics are low dose versus high dose versus registry: Mean age: 36 ± 5 years/52 ± 12 years/57 ± 15, Hypertension: 5/15/38, Diabetes-non-insulin: 1/10/29, Hyperlipidemia: 2/5/22, Prior smoker: 2/9/35, IIEF-5: 8/9/9." (PMID 31937310, 2020). "In conclusion, the results of this meta-analysis showed improvements in C-peptide level, HbA1c level, and daily exogenous insulin requirement after stem cell treatment for diabetes." (PMID 32010488, 2020). "We showed in our oncogenic Kras mouse models that STZ-induced diabetes, which is characterized by high glucose and low insulin levels, aggravated PanIN progression." (PMID 32609742, 2020). "Type 1 diabetes is a form of diabetes mellitus that results from T cell-mediated autoimmune destruction of insulin-producing pancreatic β cells as well as decreasing insulin secretion owing to anti-islet autoantibodies." (PMID 32771052, 2020). "This negatively affects diet, exercise and medication or insulin therapy compliance further exacerbating the diabetes." (PMID 33023555, 2020). "The drug dispensation pattern we observed indicates a more conservative diabetes management with more extensive insulin utilization and lower probability of receiving DPP-4i, GLP-1a or SGLT-2i when diagnosed with dementia." (PMID 32741836, 2020).
diabetes (continued). "Among them, three are diabetes pathways; two are pancreatic and insulin secretion pathways; and another two pathways are related to metabolism." (PMID 32612268, 2020). "The top 15 pathways, including two T2D-related pathways—Insulin signaling pathway (Rank 7) and Type 2 diabetes mellitus (Rank 12)—were selected for subsequent complementary pathway-to-pathway network analysis." (PMID 32294959, 2020). "Among the patients with diabetes, two were treated with insulin, 20 with oral hypoglycemic drugs, and one with only diet therapy." (PMID 32169068, 2020). "Collateral activation of IGF1R is a key concern in the use of insulin or insulin analogs for the treatment of diabetes." (PMID 31378829, 2020). "Type 2 diabetes mellitus (T2DM) is a polygenic metabolic disease described by hyperglycemia, which is caused by insulin resistance or reduced insulin secretion." (PMID 33101408, 2020). "This suggests that targeting mitochondrial Akt is a potential therapeutic approach to improve cardiac insulin-stimulated glucose oxidation in the setting of heart failure, obesity and diabetes, situations where the heart is insulin resistant." (PMID 33287820, 2020). "The onset of diabetes and HCA was highly variable, the treatment of diabetes varied from diet to insulin, and the clinical expression of HCA ranged from silent to hemorrhage." (PMID 31754975, 2020). "The hydrogel mimics the functions of the pancreas, revealing a concentration-dependent insulin release in response to glucose; an important attribute for glucose management in diabetes." (PMID 34122910, 2020). "Diabetes mellitus is a metabolic disease characterized by defective insulin secretion by pancreatic β-cells in response to glucose stimulation." (PMID 33282827, 2020). "Initiation of insulin therapy for diabetic patients is considered one of the three crises in the treatment process, alongside diabetes diagnosis itself and the diagnosis of complications." (PMID 33008418, 2020). "By the same way, prepregnancy care is also needed to prepare women with preexisting diabetes for pregnancy, such as improving glycemic control by insulin therapy." (PMID 32626786, 2020). "For instance, insulin amyloid fibril deposits have been observed in patients with insulin-dependent diabetes mellitus after insulin administration." (PMID 32398693, 2020). "In both healthy subjects and subjects with diabetes mellitus, honey decreased the levels of plasma glucose, insulin, CRP, total cholesterol, LDL-C, and TG, together with the elevation of HDL-C." (PMID 32455701, 2020). "Diabetes mellitus (DM) is a metabolic disorder characterized by chronic hyperglycemia due to defects in insulin action and secretion." (PMID 32362869, 2020). "Flavanols have antiallergic, anti-inflammatory, and anticancer properties, and they can increase insulin secretion; many plant-based drugs for treating diabetes are rich in flavanols." (PMID 32714427, 2020). "Diabetes mellitus comprises a group of carbohydrate metabolism disorders that share a common main feature of chronic hyperglycemia that results from defects of insulin secretion, insulin action, or both." (PMID 32155866, 2020). "Raptor deletion resulted in β cell failure and diabetes via reduced proliferation, cell size, cell survival, and insulin secretion." (PMID 32960890, 2020). "As insulin influences NKA function and that function directly modulates the SGLT glucose uptake, to evaluate the NKA activity in diabetes can give important information concerning the mechanisms of renal glucose handling regulation by insulin." (PMID 32377524, 2020). "Taking into consideration that autophagy is highly regulated by nutritional sensors, particularly by insulin, the insulin-resistant state or diabetes are likely influencing WAT autophagy even more than obesity itself." (PMID 32365782, 2020).